TOP1 (DNA topoisomerase I)
Diseases named in the same sentence as TOP1 in open-access papers (continued):
Sharing a sentence is not in itself a finding about the gene and the disease.
tumor (continued). "The Top1 immunoassay described in this paper has been incorporated into a Phase I clinical trial at the National Cancer Institute to assess pharmacodynamic response in tumor biopsies and determine whether baseline Top1 levels are predictive of response to indenoisoquinoline Top1 inhibitors." (PMID 23284638, 2012). "For instance, the study demonstrated that co-inhibition of TOP1 and bromodomain-containing protein 4 (BRD4) synergistically induces tumor regression." (PMID 41155268, 2025). "Protein levels and enzymatic activities of TOP1 and TDP1 have been reported to be higher in the tumor tissue of non-small cell lung cancer patients compared to normal tissue." (PMID 41155491, 2025). "This possibility is therefore more likely in COAD and LIHC tumor relative to their paired NTs where we observed increased DoG extension strength and following CPT and TOP1 knockdown that enhanced DoG expression." (PMID 38959318, 2024). "The synergism between PARPi and TOP-1 inhibitors was further demonstrated using a HCT116 xenograft model, in which a combination regimen of IT and rucaparib strongly reduced tumor growth in vivo." (PMID 39456536, 2024). "We previously demonstrated that targeting two independent arms of promoter-proximal pausing regulation through inhibition of TOP1 and BRD4 synergistically inhibited tumor growth in vitro." (PMID 37831776, 2023). "At the microscopic level of molecular interactions, JorA combines with two important tumor-promoting molecules, FASN and TOP1, and inhibits tumor progression." (PMID 37587470, 2023). "For example, we found predictive value of chr20q amplifications in CMS2 tumours treated with FOLFIRI plus cetuximab, which is evident by the significant interactions of TOP1 (pint = 0.07, FDRint < 0.2) and ARFRP1 (pint = 0.01, FDRint < 0.2)." (PMID 37666855, 2023). "We observed amplifications in chromosome arm 20q (chr20q) in 74/373 tumours (19.8%), which includes SRC, TOP1, BCL2L1, ZNF217, AURKA, GNAS and ARFRP1." (PMID 37666855, 2023). "Intriguingly, these tumor-specific gene fusion events contain one TF of SSX2 and seven oncogenes of SS18, SSX1, SSX2, BCOR, CNOT1, HIST2H2AC, and TOP1." (PMID 36118864, 2022). "Altogether, our data reveal an immune signalling mechanism activated by TOP1 poisons, which is often impaired in human SCLC tumours." (PMID 35794238, 2022). "Our results showed that the SENP3 knockdown tumour cells were most sensitive to CPT, a TOP1 inhibitor that induced DNA damage in and around the cell cycle but not as a DNA synthesis inhibitor." (PMID 35356800, 2022). "In order to further reveal anti-tumor mechanism of PTE and RE, the effect of PTE and RE on the Top1/Tdp1-mediated DNA repair pathway was further explored." (PMID 34439157, 2021). "We then performed bioanalytical measurements of exatecan in tumor versus bone marrow after dosing equimolar amounts of either CBX-12 or unconjugated exatecan in vitro and in vivo, and we compared these data to TOP1 protein levels in the corresponding samples." (PMID 34316708, 2021). "In conclusion, in addition to inhibiting the Top1/Tdp1 pathway by PTE and RE, there are other ways to inhibit tumor cells, which need to be further discovered." (PMID 34439157, 2021). "Genes CBX3, RCC1, TMOD3, and NOA1 (Cluster A) and TOP1, PDCD5, and THRAP3 (Cluster B) were upregulated for both datasets in PCa tissue vs. normal gland or normal adjacent to tumor tissue." (PMID 32640729, 2020). "We then compared proteomic results and found higher frequencies (false-discovery rate-adjusted q-value < 0.05, logistic regression) in ERCC1, TOP1 and MET protein expression in metastatic lesions compared with primary tumours." (PMID 31292535, 2019). "The mtDNA replication factors POLG2, TOP1 MT and TWNK were also found to be down-regulated in the GBM50 and GBM3 tumours." (PMID 30208958, 2018). "From the Oncomine database, we also found widespread upregulation in the expression of TOP1 and TOP2A genes in primary tumor tissues." (PMID 27315793, 2016).
tumor (continued). "Etirinotecan pegol, a long-acting Top1 inhibitor designed to provide sustained exposure to SN38, was developed with the aim of providing increased anti-tumor activity and a better safety profile compared with short-acting Top1 inhibitors." (PMID 25228368, 2014). "TOP1/CEN-2 FISH hybridization and evaluation was successful for 151 of 154 patient FFPE tumor samples (98%)." (PMID 23577133, 2013). "Once tumor specimens harboring an additional copy of TOP1 were identified, data on TOP1/CEN-20 was used to elucidate the mechanism of TOP1 gene copy increase." (PMID 23577133, 2013). "In the presence of CPTs, DNA topoisomerase I molecules are trapped on DNA as reversible Top1-CPT-DNA ternary complexes which arrest the advancing replication forks, resulting in S phase-specific killing of tumor cells." (PMID 22396773, 2012). "Notably, some TATs are crucial to the survival of tumor cells, such as CD71, TOP1, and TDGF1, which are essential for the survival of ovarian, endometrial, cervical, and other tumor cells." (PMID 40046734, 2025). "Although these pharmacodynamic assessments do not provide direct tumor-level confirmation, they offer supporting evidence for on-target activity and a cooperative mechanism of action, consistent with the synergy between TOP1 inhibition and PARP trapping." (PMID 41145467, 2025). "Our strategy of tumor-targeted delivery of chemotherapy, followed by the sequential administration of a DDR inhibitor, allowed dose escalation of both the PARP inhibitor and TOP1 inhibitor to approximately 80% of their respective single-agent MTDs." (PMID 41145467, 2025). "On the other hand, the expression of genes TOP1, EGFR, STAT3, NR3C1, VEGFA, and AR was upregulated, which could promote tumor cell growth." (PMID 38297292, 2024). "Our results confirmed that TOP1 and TOP2 play a positive role in ESCC tumor maintenance." (PMID 37088855, 2023). "Finally, it is worth highlighting that SMARCA5, which is overexpressed in different tumor types, forms a chromatin-remodeling complex with bromodomain adjacent to zinc finger domain 1B (BAZ1B) that facilitates the access of TOP1 at the replication fork." (PMID 33802597, 2021). "Future studies warrant that in a more personalized tumor-specific environment the combination of PARP and Top1 poisons may benefit patients with tumors expressing high levels of PARP1 and Top1." (PMID 33981998, 2021). "We show that CX-5461 and the TOP1 inhibitor topotecan cooperate by enhancing DDR and replication stress without generating DNA strand breaks, leading to a robust G2/M cell cycle arrest, inhibition of clonogenic survival and tumour growth in vivo." (PMID 33173151, 2021). "Human tumor cell lines exposed to Top1, HDAC, and dual Top1/HDAC inhibitors." (PMID 30300374, 2018). "TOP1 expression was significantly higher in neoplasms than in normal tissues, as evaluated using IHC (p < 0.001)." (PMID 26207989, 2015). "No TOP1 amplifications were observed in the nine cell lines investigated, but was detected in 10% of tumor samples." (PMID 23577133, 2013). "The distribution of TOP1 and CEN-2 signals was homogeneous in tumor specimens." (PMID 23577133, 2013). "Despite early reports that suggested the potential value of determining TOP1 levels in tumours, current therapeutic protocols do not take tumour expression levels of TOP1 protein or mRNA into account before giving CPT-based therapies." (PMID 23805307, 2013). "Numerous xenograft studies have demonstrated that treatment with Top1 inhibitors results in tumor regression; however, to our knowledge, none of these studies have measured target engagement by the test drugs." (PMID 23284638, 2012). "Tumor response and biomarkers for Top1 inhibitors in topotecan-nonresponsive and moderately responsive xenograft models." (PMID 23284638, 2012).
tumor (continued). "To evaluate pharmacodynamic response, we used immunofluorescence microscopy to measure the levels of TOP1, TOP1cc, RAD51, pNBS1, γH2AX, and pKAP1 in paired pre-treatment and on-treatment tumor biopsies (C1D2, 2–4 h after dosing) from 6 patients receiving LMP744 at the MTD." (PMID 40439882, 2025). "Similarly, TOP1 mRNA levels were markedly elevated in CIN or tumor tissues compared to adjacent noncancerous tissues." (PMID 39156107, 2024). "Therefore, TOP1 and c-GAS together form a signalling pathway that promotes tumour cell growth." (PMID 39735605, 2024). "DNA-containing EVs from anti-tumor topotecan (DNA topoisomerase I inhibitor)-treated breast cancer cells activate the cytokine release of dendritic cells by cGAS-STING signaling activation in cytosolic DNA-mediated innate immune responses, leading to a more robust anti-tumor immune response." (PMID 37823055, 2023). "Therefore, our current investigation also provides insights to establish a foundation to devise new synthetic lethal strategies by combining CHK1 or PARP1 inhibitors with TOP1 inhibitors to counteract WRN and NF‐κB mediated intrinsic tumor resistance in clinical settings." (PMID 35582959, 2022). "In the preclinical syngeneic mouse tumor model, it has been demonstrated that trastuzumab deruxtecan could sensitize tumors to ICI therapy by the enhanced antitumor immunity, which is activated by the delivered DNA topoisomerase I inhibitor payload." (PMID 36620535, 2022). "FL118 can show high antitumour efficacy in human tumours with low/no Top1 expression, while tumours with high Top1 expression may exhibit insensitivity to FL118 treatment." (PMID 35604033, 2022). "Furthermore, APC (p < 0.0001), ASXL1 (p < 0.0001), DNMT3B (p = 0.001), PARP4 (p = 0.002), MET (p = 0.01), TOP1 (p = 0.01), KDR (p = 0.01), SRC (p = 0.01), PAK1 (p = 0.015), ALK (p = 0.02), and MYC (p = 0.03) alterations were found to be more common in tumor samples from AO mCRC patients." (PMID 33194656, 2020). "Previously, several clinical trials using irinotecan have reported a signal of response in a subset of patients; however, these trials were conducted before the era of precision medicine, and thus the correlation between treatment response and tumor TOP1 expression was not evaluated." (PMID 29869738, 2018). "Therefore, microsatellite analysis was performed in all tumor specimens using six couples of primers targeting the 17q21 amplicon, containing TOP2A and ERBB2 genes, and 3p24 and 20q12–q13.1 loci, containing respectively TOP2B and TOP1 genes." (PMID 24216996, 2013). "It was recently observed that inhibition of TOP1 level could potentiate response of tumor cells to doxorubicin treatment without altering the expression level of TOP2A." (PMID 24103454, 2013). "Previous study shows that tumor cells were sensitive to TOP2A poisons without initiating compensatory expression of TOP2A when TOP1 was suppressed, indicating that increased response to etoposide may be independent to TOP2A expression." (PMID 24103454, 2013). "The majority (58.4%) of tumor specimens received a TOP1 Non-amplified Gain status." (PMID 23577133, 2013). "Of consideration is that the cellular and molecular pharmacology of Top1 inhibitors is complex, and while Top1 target engagement is a necessary first step in this process, it may not be a predictor for tumor response." (PMID 23284638, 2012). "Some literatures revealed that the expression level of TOP1 was not assosiated with clinicopathological features for the NSCLC patients, such as histology type, tumor differentiation and nodal status." (PMID 28355294, 2017). "To further validate that CBX-12 selectively targeted tumor and not healthy tissues, we developed a FACS-based functional assay to monitor the effect of TOP1 inhibition on TOP1 protein levels in tumor tissue and bone marrow, based on previously published methodology." (PMID 34316708, 2021).
tumor (continued). "According to the definitions used, 9% had an amplified tumor (TOP1/CEN-20 ratio ≥ 2 and TOP1/CEN-2 ratio ≥ 2), 44% had a tumor harboring a q-20 polysomy (TOP1/CEN-20 ratio ≤ 2 and TOP1/CEN-2 ratio ≥ 2), and 46% had a tumor that was neither amplified nor a polysomy." (PMID 28077117, 2017). "Top2 and PARP1 play overlapping roles to Top1 in non-dividing cells suggesting that the combination of Top1,Top2 and PARP-targeting drugs may be effective in non-dividing tumor cells." (PMID 24194914, 2013). "Overall Top1 levels in untreated HCT 116 xenografts were less variable than in A375 xenografts, which may make HCT 116 a more tractable model for certain preclinical studies of Top1 inhibitors, even though tumor growth inhibition was not as great as in the A375 model." (PMID 23284638, 2012).
infection (9 papers, 2011 to 2025). The state of being infected such as from the introduction of a foreign agent such as serum, vaccine, antigenic substance or organism. "We previously found that cellular topoisomerase I (TOP1) associates with the HSV-1 genome throughout infection." (PMID 40874743, 2025). "In all, CPT inhibition during infection results in a viral DNA replication defect, reduced replication compartment size, and increased TOP1 colocalization with viral DNA." (PMID 40874743, 2025). "To identify the steps in the infectious cycle that involve TOP1 activity, we monitored viral gene expression and DNA replication during the infection of CPT-treated cells." (PMID 40874743, 2025). "Top1 copurifies with HSV-1 DNA throughout infection, and Top1 inhibitors block HSV-2 IE gene expression and downstream events in the HSV-1 life cycle." (PMID 34696446, 2021). "TOP1 levels were maximally decreased 7 days post infection with CRE compared to tdTomato control neurons." (PMID 27231886, 2016). "However, if CPT treatment and infection occur after TOP1 knockdown alone or in combination with TOP2 knockdown, 0.14 μM CPT did not affect viral yield, and the effects of 1.4 μM CPT were significantly reduced, resulting in ~200-fold reduction in yield." (PMID 40874743, 2025). "In addition, we and others have shown that TOP1 colocalizes with viral DNA during infection." (PMID 40874743, 2025). "TOP1 has been implicated in the infection of several human herpesviruses, including HSV-2, Kaposi’s sarcoma-associated herpesvirus, and Epstein-Barr virus, suggesting that TOP1 is generally involved in processes that occur on herpes viral DNA and could be targeted for antiviral therapies." (PMID 40874743, 2025). "The results revealed that 48 h after infection with B. abortus A19, the mRNA expression of mtDNA2-6, POLG, SSBP1, and TOP1 in the BTC group was significantly greater than that in the control group." (PMID 40317067, 2025). "Infection with E. coli increased expression of polymerase gamma (POLG), single-stranded DNA-binding protein (SSBP1), TWINKLE (TWNK), and DNA topoisomerase 1 (TOP1) genes." (PMID 36430657, 2022). "The relative mRNA expression levels of Mx1 and TOP1 were significantly upregulated, whereas those of eIF4E, G6PD and PGAM1 were significantly downregulated in PK-15 cells during infection with SVA." (PMID 35632606, 2022). "We previously demonstrated that TOP1 and TOP2 are required for the optimal activation of the oxidative burst and ETI triggered by infection with P. syringae DC3000 AvrRpt2 (PstAvrRpt2)." (PMID 33894200, 2021). "Like CPT, β-Lapachone could still inhibit viral processes when added at later stages of infection, consistent with TOP1 being active on viral DNA at all stages of infection, not just during IE gene expression." (PMID 40874743, 2025). "However, TOP1 knockdown alone does not inhibit infection, suggesting that TOP1 is not essential for viral processes and that its inhibition exerts a potentially dominant negative effect on infection." (PMID 40874743, 2025).
neurological disease (8 papers, 2016 to 2025). "The stabilization of a catalytic intermediate between TOP1 and DNA leads to the formation of highly cytotoxic complexes, known as TOP1 cleavage complexes, that can cause genome instability and, if not eliminated, neurological disorders." (PMID 35188422, 2022). "Thus, changes in TOP1cc’s and TOP1 levels could contribute to a multitude of neurological disorders." (PMID 27231886, 2016).
adenocarcinoma (1 paper, 2022). A common cancer characterized by the presence of malignant glandular cells. "Altogether, the results demonstrate that WN197 at low doses with a Top1 poison activity arrest adenocarcinoma cells in G2." (PMID 35280788, 2022).
blood cancer (1 paper, 2025). "While it remains to be validated whether the increased camptothecin sensitivity of blood cancer cell lines is actually caused by TDP1 deficiencies, these observations suggest opportunities for using TOP1 poisons to better treat certain blood cancers." (PMID 39660638, 2025).
TOP1 also shares sentences with these, for which no sentence is quoted: hepatocellular carcinoma (6 papers); neurodegenerative disease (3); disorders of psychological development (2); Intellectual disability (2); non-small cell lung carcinoma (2); oral squamous cell carcinoma (2); pulmonary arterial hypertension (2); age-related macular degeneration (1); anemia (1); ankylosing spondylitis (1); autoimmune disease (1); bladder tumor (1); blastoma (1); calcinosis (1); Cerebellar atrophy (1); cervical intraepithelial neoplasia (1); chronic leukemia (1); Chronic myeloid leukemia (1); chronic periodontitis (1); colorectal adenocarcinoma (1); COVID-19 (1); dementia (1); epilepsy (1); gynecological tumor (1); head and neck squamous cell carcinoma (1); Hearing impairment (1); hepatoblastoma (1); HIV-1 infection (1); hyperphosphatemia (1); insulin-dependent diabetes mellitus (1).
A further 26 diseases each share a sentence with TOP1 in 1 paper.